UCN (urocortin)
Diseases named in the same sentence as UCN in open-access papers (continued):
Sharing a sentence is not in itself a finding about the gene and the disease.
ovarian endometriosis (3 papers, 2012 to 2025). A non-neoplastic disorder characterized by the growth of endometrial tissue in the ovaries. "Within this scientific framework, the present study was designed as exploratory research to investigate the diagnostic potential of serum and urinary Urocortin and Histone H4 as non-invasive biomarkers in ovarian endometriosis." (PMID 41011062, 2025). "In the ovarian endometriosis group, multivariate linear regression analysis revealed a statistically significant association between the rASRM score and Urocortin concentrations." (PMID 41011062, 2025). "This study aimed to evaluate the diagnostic performance and clinical relevance of Urocortin and Histone H4, assessed in both serum and urine, as potential biomarkers for ovarian endometriosis." (PMID 41011062, 2025). "In patients with ovarian endometriosis—group 1, serum Urocortin levels ranged from 2.65 to 4.30 μg/mL, with a mean value comparable to those observed in group 2 (3.59 μg/mL) and group 3 (3.70 μg/mL)." (PMID 41011062, 2025). "A multivariate linear regression model was applied to evaluate the potential influence of clinical parameters on serum Urocortin levels in patients with ovarian endometriosis." (PMID 41011062, 2025). "ROC curve analysis demonstrated that urinary Urocortin is a reliable non-invasive biomarker for ovarian endometriosis, with an area under the curve (AUC) of 0.973 (95% CI: 0.929–0.971; p = 0.001)." (PMID 41011062, 2025). "In patients with ovarian endometriosis—group 1, urinary Urocortin levels ranged from 0.41 to 4.23 μg/mL." (PMID 41011062, 2025). "In contrast, urinary Urocortin levels were significantly elevated in patients with ovarian endometriosis (2.51 ± 1.36 μg/mL), compared to both parietal endometriosis (0.13 ± 0.04 μg/mL) and controls (0.33 ± 0.18 μg/mL; p = 0.001)." (PMID 41011062, 2025). "It was showed that UCN concentrations in patients with ovarian endometriosis are higher compared to patients with benign ovarian cysts." (PMID 23093966, 2012). "Urocortin could be a potential biomarker for distinguishing ovarian endometriosis from other benign ovarian conditions." (PMID 41009445, 2025). "However, other studies have shown that serum urocortin levels are significantly higher in women with ovarian endometriosis compared to those with other benign ovarian cysts." (PMID 41009445, 2025).
atherosclerosis (2 papers, 2014 to 2015). A disease characterized by the build-up of fatty material and calcium deposition in the arterial wall resulting in partial or complete occlusion of the arterial lumen. "A number of in vitro and ex vivo investigations have shown that in cases of ischemia/reperfusion, atherosclerosis and hypertension, urocortin can protect cardiac cells from severe injury." (PMID 25667611, 2015).
cardiac ischemia (2 papers, 2016 to 2017). "It has been reported that urocortin treatment is associated with downregulation of apoptosis and improvement of myocardial injury in an ex vivo isolated cardiac ischemia reperfusion injury model." (PMID 27832152, 2016).
colitis (2 papers, 2020). Inflammation of the colon. "Studies show that in certain inflammatory disorders like colitis, there is an upregulation in the expression of urocortin mRNA." (PMID 32120970, 2020).
melanoma (2 papers, 2021 to 2023). A malignant, usually aggressive tumor composed of atypical, neoplastic melanocytes. "Then, we identified 9 LR pairs (“BMP6- > HJV” 、"CCL8- > ACKR4” 、"DLL3- > NOTCH3"、"DSC3- > DSG3"、"GHRH- > GHRHR” 、"LRRC4B- > PTPRF"、"SEMA4D- > PLXNB1"、"SFRP1- > FZD6"、"UCN- > CRHR1′′) as key LR pairs in melanoma prognosis through Lasso Cox regression and Multiple Stepwise Regression." (PMID 36777724, 2023). "It has been suggested that in human melanoma cells, CRH and urocortin regulate TYRP1 gene expression via NURR1/NUR77 production." (PMID 34884858, 2021).
neuroblastoma (2 papers, 2022 to 2025). Neuroblastoma (NB) is the most common solid, extracranial childhood tumor. "Peptides (angiotensin II, neuropeptide Y, neurotensin, substance P) act as oncogenic agents in neuroblastoma, whereas others (adrenomedullin, corticotropin-releasing factor, urocortin, orexin) exert anticancer effects against neuroblastoma." (PMID 40331938, 2025). "We identified differential methylation of genes that have been related to cancers such as lymphoma (WNT6, TP73, and CD37), leukaemia (MEIS1, HOXA4, and HOXA5) or neuroblastoma (TP73), as well as genes related to cardiovascular diseases (UCN, PRDM16, TCAP, ALOX5)." (PMID 35354948, 2022).
osteoarthritis (2 papers, 2022 to 2023). A noninflammatory degenerative joint disease occurring chiefly in older persons, characterized by degeneration of the articular cartilage, hypertrophy of bone at the margins and changes in the synovial membrane. "Urocortin (Ucn) is a peptide that has been shown to have some potential use in rheumatoid arthritis and osteoarthritis, and it is hypothesised that it can be exploited for treating osteoporosis." (PMID 37313093, 2023).
renal carcinoma (2 papers, 2013 to 2025). A carcinoma arising from the epithelium of the renal parenchyma or the renal pelvis. "Considering that previous analyses support the relevance of the UCN system for human carcinogenesis including also renal cancer, we hypothesize that alteration of CRHBP as a putative modulator of UCN levels may also contribute to the development and course of cc-RCC." (PMID 23607589, 2013).
Alcohol (1 paper, 2016). "This review will focus primarily on findings stemming from preclinical studies and how they contribute to our understanding of CRF/urocortin mechanisms in alcohol dependence." (PMID 27818644, 2016). "The impact of alcohol exposure on CRF/urocortin signaling and plasticity will be discussed, as potential neuroadaptive mechanisms recruited during the establishment of alcohol dependence." (PMID 27818644, 2016). "Also, apart from its role in more traditional brain stress circuits, this review will discuss increasing evidence for the CRF system as a direct modulator of brain reward pathways, suggesting that CRF/urocortin signaling may also modulate alcohol’s effects at earlier stages of alcohol dependence." (PMID 27818644, 2016).
Alzheimer disease (1 paper, 2026). A progressive, neurodegenerative disease characterized by loss of function and death of nerve cells in several areas of the brain leading to loss of cognitive function such as memory and language. "Cholinergic neurons of the preganglionic Edinger-Westphal nucleus (EW) are involved in Alzheimer's disease (AD), however, the role of urocortin 1 (UCN1) positive peptidergic neurons of the centrally projecting EW (EWcp) remains unclear." (PMID 41876672, 2026).
asthma (1 paper, 2022). "In addition, it is revealed that the attenuation of surfactant-d (SP-D) and urocortin (UCN) is another mechanism that is associated with the anti-asthma effects of polydatin." (PMID 36235012, 2022).
cardiac arrest (1 paper, 2016). Cessation of breathing and/or cardiac function. "Urocortin was able to induce early improvement and stabilization of circulatory failure in the post-cardiac arrest period, thus improving survival outcome in experimental animals, as shown in this study." (PMID 27832152, 2016). "In our study, we found that urocortin can exert positive inotropic and lusitropic effects in the cardiac arrest model." (PMID 27832152, 2016). "In our study, we found that urocortin treatment was able to reduce myocardial apoptosis after cardiac arrest and resuscitation in addition to having beneficial hemodynamic effects." (PMID 27832152, 2016). "Activation of downstream signal transduction pathways supports the reduced cardiomyocyte damage as a result of urocortin-related cardioprotective effects, and may contribute to improving the post-cardiac arrest myocardial dysfunction and survival outcome." (PMID 27832152, 2016). "In this study, we found that urocortin treatment can activate key pro-survival signal transducers including Akt, ERK and STAT-3 after cardiac arrest and resuscitation." (PMID 27832152, 2016).
clear cell renal cell carcinoma (1 paper, 2022). "Urocortin (UCN), belonging to the corticotropin-releasing hormone (CRH) family, is involved in an immune-related signature in the clear cell renal cell carcinoma (ccRCC or KIRC)." (PMID 35831825, 2022).
diabetic cardiomyopathy (1 paper, 2015). Diabetic cardiomyopathy is a disorder of the heart muscle in people with diabetes. "However, the role and mechanism of urocortin in protecting against diabetic cardiomyopathy (DCM) has not yet been elucidated." (PMID 25667611, 2015).
hyperandrogenism (1 paper, 2020). Excessive secretion of androgens from the adrenal glands or gonads. "The study also reports the enhanced gene expression pattern of urocortin in the liver of the hyperandrogenism animal model of PCOM." (PMID 32120970, 2020). "In this context, the identification of urocortin during an inflammatory state in the liver and hyperandrogenism opens a new avenue on the role of androgens in the regulation of urocortin." (PMID 32120970, 2020).
lichen (1 paper, 2024). "Similarly, nuclear UCN expression was higher in VSCC cases (mean H-score = 26), compared to both VIN (U = 274, Z = − 2, p = 0.047 two tailed) and lichen cases (U = 159.5, Z = − 4.7, p < 0.001 two tailed)." (PMID 37382757, 2024). "Immunohistochemical expression of CRH, urocortin (UCN), FasL and their receptors CRHR1, CRHR2 and Fas was studied in vulvar tissue sections obtained from patients with histologically confirmed diagnosis of lichen, vulvar intraepithelial neoplasia (VIN) and vulvar squamous cell carcinoma (VSCC)." (PMID 37382757, 2024).
liver cancer (1 paper, 2021). An epithelial or non-epithelial malignant neoplasm that arises from the liver. "Importantly, only a few genes were previously implicated with liver cancer development (ATG4B, CCR5, MCM6, and UCN), whereas most of the epidrivers were newly identified." (PMID 34375307, 2021).
migraine (1 paper, 2024). "The urocortin 1 (UCN1)–expressing centrally projecting Edinger–Westphal (EWcp) nucleus is influenced by circadian rhythms, hormones, stress, and pain, all known migraine triggers." (PMID 38875125, 2024).
minimal change disease (1 paper, 2022). "miR-324 in non-malignant diseases (DCI, Delayed cerebral infarction; IEC, intestinal epithelial cells; MCD, minimal change disease; HG, high glucose; Ucn, Urocortin; OGD/R, oxygen-glucose deprivation/reoxygenation; NOF, neck of the femur; EX, aerobic exercise; SED, sedentary)." (PMID 36035118, 2022).
Myocardial fibrosis (1 paper, 2015). "Urocortin inhibits myocardial fibrosis and inflammation in diabetic rats, which is associated with the inhibition of TGF-β1 and CTGF expression and the Akt/GSK-β signaling pathways." (PMID 25667611, 2015). "In conclusion, the results of the present study support the hypothesis that urocortin markedly inhibits the development of cardiac dysfunction, myocardial fibrosis and inflammation in diabetic rats." (PMID 25667611, 2015).
osteoporosis (1 paper, 2023). A condition of reduced bone mass, with decreased cortical thickness and a decrease in the number and size of the trabeculae of cancellous bone (but normal chemical composition), resulting in increased fracture incidence. "The anti-resorptive molecule, urocortin, is believed to have a potential role in regulating bone remodelling and thus osteoporosis." (PMID 37313093, 2023). "The use of urocortin is an exciting prospect, which will hopefully continue to be fully exploited so that it can be translated into clinical practice and revolutionise osteoporosis treatment." (PMID 37313093, 2023).
Premature rupture of membranes (1 paper, 2009). Premature rupture of membranes (PROM) is a condition which occurs in pregnancy when the amniotic sac ruptures more than an hour before the onset of labor. "More specifically the amniotic fluid levels of urocortin in women with premature rupture of membranes were not higher than in women at term (1.64 ± 0.54 ng/mL versus 1.6 ± 0.49 ng/mL." (PMID 19893766, 2009).
prostate carcinoma (1 paper, 2023). A carcinoma that arises from epithelial cells of the prostate gland. "On the contrary, in the RM‐1 mouse prostate cancer cell line, the presence of urocortin did not support apoptosis, while CRF had the opposite effect." (PMID 36971048, 2023).
retinal degeneration (1 paper, 2023). Degeneration of the retina. "Meanwhile, urocortin (UCN), which encodes a peptide from the corticotropin-releasing factor family, protects against retinal degeneration, and it has been shown to be expressed in post-ONC in the two sustained αRGC types, especially in response to AAV, according to single-cell RNA-sequencing." (PMID 38203368, 2023).
Sepsis (1 paper, 2014). Sepsis is defined as life-threatening organ dysfunction caused by a dysregulated host response to infection. "VIP and urocortin protect from the lethal effect of E.coli and cecal ligation and puncture (CLP)-induced sepsis and this protection is paralleled by a decrease in the systemic levels of high mobility group box 1 (HMGB1)." (PMID 25101851, 2014).
tumor (14 papers, 2017 to 2026). "In BALB/c mouse xenograft models, UCN silencing remodeled the tumor microenvironment by increasing CD8+ T cell infiltration and reducing regulatory T cells (p < 0.01)." (PMID 42122169, 2026). "ENTPD2 and UCN displayed more restricted expression patterns, primarily in fibroblasts, suggesting their specialized roles in the tumor microenvironment." (PMID 40243888, 2025). "Perturbation of UCN expression notably curtailed tumor cell proliferation, underscoring their potential as a target for innovative cancer therapies." (PMID 39336730, 2024). "Further investigation revealed increased protein expression levels of UCN in tumor tissues compared to normal tissues in CRC patients but not GABRD." (PMID 39336730, 2024). "The correlation between UCN nuclear positivity and tumor differentiation warrants further investigation." (PMID 37382757, 2024). "Considering the increased protein expression levels of UCN in tumor tissues compared to normal tissues in the CRC patients, UCN serves as the key gene in the prognostic model." (PMID 39336730, 2024). "According to the Mann–Whitney U analysis of the tissue microarray data, there was a significant difference in sex, tumor lymph node metastasis, and clinical stage between the groups with low and high UCN-1 expression." (PMID 38546882, 2024). "Combined with immune infiltration analysis and gene perturbation assays, UCN is the key gene promoting tumor development in the model." (PMID 39336730, 2024). "A reduction in the expression of Ki-67 in xenograft tumors indicated that UCN-1 knockdown curbed tumor growth." (PMID 38546882, 2024). "We found that UCN was overexpressed in tumor samples compared to normal samples in both TCGA and ICGC cohorts." (PMID 36785707, 2023). "Compared with the para-cancerous normal tissues, most tumor tissues were immunoreactive for UCN-1." (PMID 38546882, 2024). "Our exploration into immune infiltration and the roles of the key gene, UCN, in the tumor microenvironment revealed the following notable finding: Increased UCN expression correlates with reduced immune cell presence in CRC patients, as indicated by single-cell RNA sequencing data." (PMID 39336730, 2024). "As the expression of UCN-1 was positively correlated with tumor lymph node metastasis, UCN-1 may act as a promoting factor for CRC cell migration." (PMID 38546882, 2024). "According to Wang and Li, urocortin can inhibit the growth of tumor cells by activating CRF1." (PMID 36971048, 2023). "Furthermore, to explore whether silencing UCN could as well as affect the migration ability of tumor cells, we performed the transwell migration assay and proved that knocking down UCN could vastly attenuated tumor migration." (PMID 36785707, 2023). "In order to investigate whether UCN impacted oxidative stress in tumor cells actually, we constructed a stable knocking down UCN ccRCC cell lines and employed a series of specific kits to determine the ROS through DCFH-DA and the superoxide content by dihydroethidium." (PMID 36785707, 2023). "Nuclear localization of UCN was demonstrated in both premalignant and VSCC lesions, with staining being significantly intensified in carcinomas, particularly in the less differentiated tumor areas or in the areas at invasive tumor front." (PMID 37382757, 2024).
cancer (8 papers, 2017 to 2024). A tumor composed of atypical neoplastic, often pleomorphic cells that invade other tissues. "Increasing evidence has shown the critical role of UCN in the development of diverse malignant tumors in humans." (PMID 38546882, 2024). "Functional experiments showed that UCN gene interference in the CRC cell lines significantly decreased cancer cell proliferation, underscoring UCN’s role in intestinal immunity modulation." (PMID 39336730, 2024). "Overall, 51 of 93 (54.8%) cases presented high UCN-1 expression in CRC tissues, whereas 3 of 87 (3.4%) cases showed high UCN-1 levels in para-carcinoma tissues." (PMID 38546882, 2024). "However, it was also suggested that urocortin may have a dual role in cancer, since it differentially binds to CRFR1 or CRFR2 and either activates or blocks the Bcl-2/Bax/caspase-9 axis, leading to apoptosis or survival, respectively." (PMID 31238876, 2019). "These genes are PLAUR, UCN, PABPC1L, SLC16A12, NFE2L3, and KCNAB1, and some of them have been previously reported in multiple types of cancer." (PMID 35211477, 2021). "Additionally, the study sheds light on the tumorigenic capabilities of UCN and GABRD, linking these genes to pivotal pathways known to drive cancer progression, such as MYC targets V1, MYC targets V2, and DNA repair pathways." (PMID 39336730, 2024). "Numerous studies have revealed that UCN-1 is involved in the development of several cancer types but its contribution to CRC development had not been elucidated and the relationship between CRC and UCN-1 remained unclear." (PMID 38546882, 2024).
cardiovascular diseases (3 papers, 2014 to 2022). "Urocortin has been shown to exert powerful protective effects on various cardiovascular disease models." (PMID 25667611, 2015).
UCN also shares sentences with these, for which no sentence is quoted: mood disorder (3 papers); acute myocardial infarction (2); Anorexia (2); breast carcinoma (2); colorectal cancer (2); congestive heart failure (2); endometrial adenocarcinoma (2); Hypertension (2); posttraumatic stress disorder (2); rheumatoid arthritis (2); skeletal system disorder (2); stress-related disorder (2); Arthritis (1); astrocytomas (1); colon adenocarcinoma (1); coronary artery disease (1); Crohn disease (1); drug dependence (1); Endometrium (1); gastric adenocarcinoma (1); Headache (1); hearing loss (1); hepatocellular carcinoma (1); hypertrophic cardiomyopathy (1); hypertrophy (1); infection (1); leukaemia (1); lymphoma (1); ovarian carcinoma (1); ovarian teratoma (1).
A further 9 diseases each share a sentence with UCN in 1 paper.